ZSWIM8 (zinc finger SWIM-type containing 8)
Description:
Substrate recognition component of a SCF-like E3 ubiquitin-protein ligase complex that promotes target-directed microRNA degradation (TDMD), a process that mediates degradation of microRNAs (miRNAs). The SCF-like E3 ubiquitin-protein ligase complex acts by catalyzing ubiquitination and subsequent degradation of AGO proteins (AGO1, AGO2, AGO3 and/or AGO4), thereby exposing miRNAs for degradation. Specifically recognizes and binds AGO proteins when they are engaged with a TDMD target. May also act as a regulator of axon guidance: specifically recognizes misfolded ROBO3 and promotes its ubiquitination and subsequent degradation. Plays an essential role for proper embryonic development of heart and lung (By similarity). Controls protein quality of DAB1, a key signal molecule for brain development, thus protecting its signaling strength. Mechanistically, recognizes intrinsically disordered regions of DAB1 and eliminates misfolded DAB1 that cannot be properly phosphorylated (By similarity). (Microbial infection) Participates in Zika virus inhibition of IFN signaling by acting as a scaffold protein to connect ZSWIM8/CUL3 ligase complex and STAT2, leading to STAT2 degradation.
Synonyms: KIAA0913; 4832404P21Rik
Tractability: Antibody: the Human Protein Atlas places it where antibodies can reach. PROTAC: ubiquitination databases record sites on it; its protein half-life has been measured.
Gene: Protein-coding gene on chromosome 10 (73,785,606 to 73,801,797, forward strand). Ensembl gene ENSG00000214655.
Subcellular location: Cytoplasm, cytosol
Subcellular location (Human Protein Atlas): Cytosol; Plasma membrane
Pathways (Reactome):
Developmental Biology: Regulation of expression of SLITs and ROBOs
Gene Ontology:
Molecular function: ubiquitin-like ligase-substrate adaptor activity; zinc ion binding
Biological process: positive regulation of miRNA catabolic process; proteasome-mediated ubiquitin-dependent protein catabolic process; protein quality control for misfolded or incompletely synthesized proteins; protein ubiquitination; target-directed miRNA degradation
Cellular component: Cul3-RING ubiquitin ligase complex; Cul2-RING ubiquitin ligase complex; cytosol
Genetic constraint (gnomAD): Loss-of-function variants: 27 observed, 163.4 expected, observed/expected ratio (o/e) 0.17, 90% interval 0.12 to 0.23. The upper end of that interval is the gene's LOEUF score, 0.23, which puts it in group 1 of 6, group 1 being the genes least tolerant of losing a copy. Missense variants: 1,627 observed, 2,431.6 expected, observed/expected ratio (o/e) 0.67, 90% interval 0.64 to 0.7. Synonymous variants: 958 observed, 960.27 expected, observed/expected ratio (o/e) 1, 90% interval 0.94 to 1.05.
Homologues: Orthologues: macaque ZSWIM8 (99% identical), dog ZSWIM8 (99% identical), pig ZSWIM8 (98% identical), rabbit ZSWIM8 (98% identical), guinea pig ZSWIM8 (97% identical), mouse Zswim8 (97% identical), rat Zswim8 (97% identical), chimpanzee ZSWIM8 (94% identical), tropical clawed frog zswim8 (78% identical), zebrafish zswim8 (76% identical), Drosophila melanogaster Dora (45% identical), Caenorhabditis elegans ebax-1 (25% identical). Paralogues in human: ZSWIM6 (18% identical), ZSWIM5 (18% identical), ZSWIM4 (18% identical).
Diseases named in the same sentence as ZSWIM8 in open-access papers:
ZSWIM8 is named in the same sentence as 18 diseases in open-access papers, as found by Europe PMC text mining. Sharing a sentence is not in itself a finding about the gene and the disease. The quoted sentences say what the papers report.
schizophrenia (2 papers, 2020 to 2023). A major psychotic disorder characterized by abnormalities in the perception or expression of reality. "Among highly ranked genes lacking SFARI Gene scores and OMIM annotations, previous studies suggest association with NDDs and schizophrenia [OBSCN, PLEC, RYR2, ZSWIM8], cortical formation and thickness [LAMA5, GOLGA3), and neurodegenerative diseases (PKHD1, DNAH1]." (PMID 35596027, 2023). "Seven out of 18 genes are associated with neurological diseases: Alzheimer’s disease (CPT1A, SUFU, ZSWIM8, PDCD4), schizophrenia (HTT, NBEAL2) and Parkinson disease (PRDM13)." (PMID 32599769, 2020). "Interestingly, there were seven genes associated with neurological disorders, including Alzheimer’s disease (CPT1A, SUFU, ZSWIM8, PDCD4), schizophrenia (HTT, NBEAL2) and Parkinson’s disease (PRDM13)." (PMID 32599769, 2020).
acromelic frontonasal dysostosis (1 paper, 2022). "Although we know that no pathological phenotype is expressed in the examined individual, disease such as Acromelic Frontonasal Dysostosis is associated with ZSWIM8." (PMID 35456375, 2022).
Cyanosis (1 paper, 2023). Bluish discoloration of the skin and mucosa due to poor circulation or inadequate oxygenation of arterial or capillary blood. "Although the VSDs might have contributed to the cyanosis observed in Zswim8−/− newborns, they did not appear sufficiently severe to explain the highly penetrant lethality." (PMID 37532519, 2023).
cancer (2 papers, 2022 to 2025). A tumor composed of atypical neoplastic, often pleomorphic cells that invade other tissues. "ZSWIM8 is expressed in various cancer cells, including papillary thyroid carcinoma, non-small cell lung cancer, and human glioma, while ZSWIM5 is involved in embryonic and neural development." (PMID 41007757, 2025). "In addition to ZSWIM8, other members of the SWIM-type zinc finger family, including ZSWIM4, ZSWIM5, and ZSWIM6, have been implicated as potential cancer targets and biomarkers." (PMID 41007757, 2025). "In addition, taken together with the data presented here, Pldo/ZSWIM8 could also have a role in cancer cells because its LOF might enhance the migratory capacity of invasive metastatic cells." (PMID 35940847, 2022).
genetic disorder (1 paper, 2022). "As suggested by Yamamoto, Bellen, and colleagues, Pldo/ZSWIM8 appears to be linked to a genetic disorder in humans affecting the nervous system." (PMID 35940847, 2022).
ZSWIM8 also shares sentences with these, for which no sentence is quoted: Alzheimer disease (1 paper); chronic myelogenous leukemia (1); fibrocystic disease (1); neurodegenerative disease (1); neurological diseases (1); osteosarcoma (1); Parkinson disease (1); renal cell adenocarcinoma (1); renal clear cell carcinoma (1); Respiratory distress (1); severe acute respiratory syndrome (1); viral infection (1); ZIKV infection (1).